ENSG00000254051 (NADH dehydrogenase )
Diseases named in the same sentence as ENSG00000254051 in open-access papers (continued):
Sharing a sentence is not in itself a finding about the gene and the disease.
cancer (22 papers, 2010 to 2025). A tumor composed of atypical neoplastic, often pleomorphic cells that invade other tissues. "In the future, the adequacy of the prediction of pathogenicity used here should be confirmed by examining the influence of each missense mutation in cancer cells on complex I (NADH dehydrogenase) activity and ROS generation." (PMID 29138417, 2017). "MtDNA sequencing revealed loss-of-function mutations in NADH dehydrogenase subunits, highlighting the role of deregulated metabolism in this and other cancers." (PMID 25859550, 2015). "Cancer cells have more mutations in their mitochondrial DNA (mtDNA) than do normal cells, and pathogenic mutations in the genes encoding mitochondrial NADH dehydrogenase (ND) subunits have been found to enhance the invasive and metastatic ability of various tumour cells in animal experiments." (PMID 29138417, 2017). "NAD+ regeneration by mitochondrial complex I NADH dehydrogenase is important for cancer cell proliferation." (PMID 39873399, 2025). "The observed increase in NADH dehydrogenase expression aligns with broader metabolic shifts that enable resistance across multiple cancer types." (PMID 41360907, 2025). "Recent research evidence has revealed that lncRNA ZFAS1 can encode a small peptide to down-regulate NADH dehydrogenase expression (NDUFA6, NDUFB11 and NDUFB4) to enhance ROS production, thus promoting cancer development." (PMID 34888249, 2021). "In this study, we report that in human cancer cells, metformin inhibits mitochondrial complex I (NADH dehydrogenase) activity and cellular respiration." (PMID 24843020, 2014). "Importantly, the anti-cancer effects of Complex I inhibitors were abolished when the inhibitor-resistant Saccharomyces cerevisiae NADH dehydrogenase NDI1 was overexpressed, proving that Complex I assists cancer by providing NAD+." (PMID 38526218, 2024). "Finally, we found that the experimentally validated translated lncRNA ZFSA1 promoted cancer cell migration by elevating cellular ROS production via the expression downregulation of NADH dehydrogenase expression (NDUFA6, NDUFB4, and NDUFB11)." (PMID 31781169, 2019). "The accumulation of NADH in cancer cells may inhibit NADH-dehydrogenase, thus decreasing α-ketoglutarate oxidation." (PMID 30551591, 2018). "Our results suggest that the NADH dehydrogenase activity of regenerating NAD+ maintains SIRT activity and suppresses antiproliferative p21Cip1 expression in cancer cells." (PMID 39873399, 2025). "Down-regulate NADH dehydrogenase expression (NDUFA6, NDUFB4, and NDUFB11) to enhance ROS production and thus promote cancer cell migration." (PMID 34888249, 2021). "In PA28 overexpressing cancer cell model 3-BrPA application harmed mitochondrial NADH dehydrogenase activity mildly and significantly failed to inhibit lactate production." (PMID 32948135, 2020). "Thus, the low rates of the State 3 oxidation of glutamate and citrate in cancer mitochondria were not caused by low activity of the ATP/ADP carrier, ATP synthase, or activities of Complexes III and IV, but rather, by low activity of Complex I (NADH dehydrogenase)." (PMID 23951286, 2013).
tumor (12 papers, 2014 to 2025). "The NDUFA13 gene encodes a NADH dehydrogenase enzyme, a part of the electron transport chain in mitochondria that can function as a tumour suppressor (Pinto and Máximo, 2018)." (PMID 37529293, 2022). "Previous study showed that mitochondrial ND6 (mitND6) gene missense mutation resulted in NADH dehydrogenase deficiency and was associated with tumor metastasis in several mouse tumor cell lines." (PMID 25934296, 2015). "On the one hand, S100A4 promotes tumor progression by up-regulating mitochondrial complex I subunit NADH dehydrogenase (ubiquinone) Fe-S protein 2 to enhance invasion and metabolic reprogramming." (PMID 40853920, 2025). "Tumor cells critically depend on mitochondrial Complex I (NADH dehydrogenase) activity to sustain NAD+/NADH balance and tricarboxylic acid (TCA) cycle functionality." (PMID 41514605, 2025). "Thus, as already applied for mitochondrial diseases, we propose NDI1 as a useful tool to uncover NADH dehydrogenase inhibition in specific tumor cells and bypass it in order to assess its potential contribution to neoplastic transformation." (PMID 35393510, 2022). "These compounds have various bioactivities, such as broad-spectrum antimicrobial activity, anti-trichomonas, anti-tumor, and inhibitory activities against H+/K+-ATPase, mitochondrial oxidative phosphorylation, NADH dehydrogenase, and phospholipase C, while they also have a little toxicity." (PMID 31671653, 2019).
infection (6 papers, 2012 to 2023). The state of being infected such as from the introduction of a foreign agent such as serum, vaccine, antigenic substance or organism. "However, PmCQ2 infection also caused reduction of all NADH dehydrogenase subunits (ND1~ND6), implying the oxidative phosphorylation of chicken was impaired, which was unfavorable to M2 macrophage activation." (PMID 32851030, 2020). "Additionally, serum mtDNA release (indicating NADH dehydrogenase activity and cytochrome c oxidation) was 1.5- to 2-fold higher in patients with rt269I infection than in patients with rt269L infection." (PMID 36997871, 2023). "NQR is the ion-pumping NADH dehydrogenase that requires the least amount of iron for its assembly (1 or 2 atoms per molecule), which could allow an active bioenergetic metabolism and cell survival during infection, in particular when the immune response has been mounted." (PMID 32324772, 2020). "Our results show that a defective NADH dehydrogenase activity leads to an increase in the NADH/NAD+ ratio and a depletion of NAD(H) intracellular pools, which is known to exert a bactericidal effect during infection." (PMID 38032200, 2023).
neurodegenerative disease (5 papers, 2015 to 2024). A disorder of the central nervous system characterized by gradual and progressive loss of neural tissue and neurologic function. "In contrast, the downregulation of NADH dehydrogenase subunit genes such as nd4 can be associated with neurodegenerative disease." (PMID 37367494, 2023). "It has been shown that neoechinulin A inhibits SIN-1-induced activation of caspase-3-like proteases and increases NADH-dehydrogenase activity, which helps to prevent neuronal cell death in neurodegenerative diseases." (PMID 38792694, 2024).
metabolic disorders (3 papers, 2014 to 2024). "Because NADH dehydrogenase is central to energy production in the cell, its malfunction may result in a wide range of metabolic disorders." (PMID 25153900, 2014).
psychiatric disorder (2 papers, 2025). A disorder characterized by behavioral and/or psychological abnormalities, often accompanied by physical symptoms. "Moreover, mutations in MT-ND6 and MT-ND5, both components of NADH dehydrogenase, have been associated with various psychiatric disorders." (PMID 40495250, 2025).
neurological diseases (1 paper, 2023). "Mutations in subunits of the mitochondrial NADH dehydrogenase cause mitochondrial complex I deficiency, a group of severe neurological diseases that can result in death in infancy." (PMID 37399212, 2023).
ENSG00000254051 also shares sentences with these, for which no sentence is quoted: depression (3 papers); mitochondrial disease (3); adenocarcinoma (2); metabolic syndrome (2); migraine (2); mitochondrial myopathies (2); Parkinson (2); type 2 diabetes (2); acute myocardial infarction (1); adenoma (1); alcoholic fatty liver disease (1); asthma (1); Ataxia (1); atherosclerosis (1); bacteremia (1); cardiovascular disease (1); carotid atherosclerosis (1); Cerebral ischemia (1); cholangiocarcinoma (1); congenital heart disease (1); dementia (1); diabetic cardiomyopathy (1); Dystonia (1); Encephalopathy (1); hematological disease (1); hereditary optic neuropathy (1); Huntington disease (1); Hyperglycemia (1); Hypertension (1); hypertrophic cardiomyopathy (1).
A further 16 diseases each share a sentence with ENSG00000254051 in 1 paper.